AK4 (adenylate kinase 4)
Description:
Broad-specificity mitochondrial nucleoside phosphate kinase involved in cellular nucleotide homeostasis by catalyzing nucleoside-phosphate interconversions. Similar to other adenylate kinases, preferentially catalyzes the phosphorylation of the nucleoside monophosphate AMP with ATP as phosphate donor to produce ADP. Phosphorylates only AMP when using GTP as phosphate donor. In vitro, can also catalyze the phosphorylation of CMP, dAMP and dCMP and use GTP as an alternate phosphate donor. Moreover, exhibits a diphosphate kinase activity, producing ATP, CTP, GTP, UTP, TTP, dATP, dCTP and dGTP from the corresponding diphosphate substrates with either ATP or GTP as phosphate donors. Plays a role in controlling cellular ATP levels by regulating phosphorylation and activation of the energy sensor protein kinase AMPK. Plays a protective role in the cellular response to oxidative stress.
Synonyms: AK3; AK3L1; AK 4; AK3L2
Tractability: Small molecule: a structure with a bound ligand is known; it has a high-quality binding pocket. PROTAC: ubiquitination databases record sites on it; its protein half-life has been measured.
Target class: Enzyme; Transferase
Gene: Protein-coding gene on chromosome 1 (65,146,902 to 65,232,145, forward strand). Ensembl gene ENSG00000162433.
Subcellular location: Mitochondrion matrix
Subcellular location (Human Protein Atlas): Mitochondria
Pathways (Reactome):
Metabolism: Interconversion of nucleotide di- and triphosphates
Gene Ontology:
Molecular function: AMP kinase activity; CMP kinase activity; dAMP kinase activity; dCMP kinase activity; nucleoside diphosphate kinase activity; nucleoside monophosphate kinase activity; nucleoside triphosphate adenylate kinase activity; protein binding; ATP binding; nucleobase-containing compound kinase activity; phosphotransferase activity, phosphate group as acceptor
Biological process: AMP metabolic process; ATP metabolic process; cellular response to hypoxia; GTP metabolic process; regulation of oxidative phosphorylation; ribonucleoside diphosphate biosynthetic process; nucleobase-containing small molecule interconversion; nucleoside triphosphate biosynthetic process; ADP biosynthetic process; nucleobase-containing small molecule metabolic process
Cellular component: mitochondrial matrix; mitochondrion
Genetic constraint (gnomAD): Loss-of-function variants: 11 observed, 19.34 expected, observed/expected ratio (o/e) 0.57, 90% interval 0.36 to 0.94. The upper end of that interval is the gene's LOEUF score, 0.94, which puts it in group 3 of 6, group 1 being the genes least tolerant of losing a copy. Missense variants: 166 observed, 240.53 expected, observed/expected ratio (o/e) 0.69, 90% interval 0.61 to 0.79. Synonymous variants: 82 observed, 93.11 expected, observed/expected ratio (o/e) 0.88, 90% interval 0.74 to 1.06.
Homologues: Orthologues: macaque AK4 (99% identical), dog AK4 (96% identical), rabbit AK4 (92% identical), mouse Ak4 (90% identical), rat Ak4 (89% identical), guinea pig AK4 (79% identical), tropical clawed frog ak4 (78% identical), zebrafish ak4 (63% identical), Caenorhabditis elegans F13E6.2 (25% identical), Drosophila melanogaster CG9541 (22% identical). Paralogues in human: AK4P3 (99% identical), AK3 (59% identical), AK2 (41% identical), AK5 (26% identical), AK7 (26% identical), AK8 (26% identical), AK1 (25% identical), CMPK1 (25% identical), AK9 (22% identical).
Diseases named in the same sentence as AK4 in open-access papers:
AK4 is named in the same sentence as 39 diseases in open-access papers, as found by Europe PMC text mining. Sharing a sentence is not in itself a finding about the gene and the disease. The quoted sentences say what the papers report.
lung carcinoma (19 papers, 2018 to 2025). "AK4 is overexpressed in lung cancer, and high AK4 expression is associated with poor survival in many cancers." (PMID 40593461, 2025). "In lung cancer, the underlying mechanisms by which AK4 drives metastasis include the stabilization of HIF-1α and inhibition of AMPK." (PMID 34638712, 2021). "The AK4 isoform increased expression has been associated with a poor clinical outcome marker for lung cancer as well as for glioma patients." (PMID 32509571, 2020). "AK4 overexpression promotes lung cancer metastasis by enhancing HIF-1α stability and epithelial–mesenchymal transition (EMT) under hypoxic conditions." (PMID 36982634, 2023). "The loss of AK4 expression led to the suppression of the invasive potential of lung cancer cell lines, whereas AK4 overexpression promoted the invasion in vitro and in vivo." (PMID 36982634, 2023). "Adenylate kinase 4 (AK4) was reported to modulate oxidative stress that enhanced lung cancer metastasis." (PMID 36504353, 2023). "AK4 has been reported to act as an oncogene in several types of human cancer, including ovarian cancer, lung cancer, HER2-positive breast cancer and bladder cancer." (PMID 36476264, 2023). "Circ-ABCB10 increases the expression of AK4, promotes lung cancer progression, and sensitizes lung cancer cells to cisplatin via sponging miR-556-3p." (PMID 36338714, 2022). "Significantly increased AK4 abundance was detected in lung cancer cells exposed to hypoxia, which is relevant to our work." (PMID 34440794, 2021). "Hypoxia was reported to upregulate AK4 in human cancer cell lines such as HeLa (cervical cancer), A549 (lung carcinoma), and SHSY5Y (neuroblastoma) as well as in mouse chondroprogenitor cells and immortalized HEK293 (human embryonic kidney) cells." (PMID 34638712, 2021). "In lung cancer, AK4 operates as an upstream HIF-1α regulator by stabilizing HIF-1α through the inhibition of its hydroxylation and subsequent degradation, whereas in macrophages it acts by enhancing both HIF-1α gene transcription and protein stability." (PMID 34638712, 2021). "Results from recent studies have shown that high expressions of AK4 promote lung cancer metastasis by enhancing HIF-1α stability and EMT under conditions of hypoxia." (PMID 34217310, 2021). "Overexpression of AK4 promoted lung cancer metastasis by enhancing hypoxia-inducible factor HIF-1 stability and epithelial-to-mesenchymal transition under hypoxia." (PMID 32509571, 2020). "Formerly, a study suggested the correlation of high AK4 level with poor survival in lung cancer, but the detailed role of AK4 in lung cancer progression and cell response to cisplatin was first revealed in our study." (PMID 31931771, 2020). "In summary, all these data from this study indicate that targeting circ-ABCB10/miR-556-3p/AK4 pathway enhance sensitivity of lung cancer cells to cisplatin." (PMID 31931771, 2020). "Then, we studied the potential influence of AK4 on lung cancer cell progression and sensitivity to cisplatin." (PMID 31931771, 2020). "Circ-ABCB10 knockdown enhances sensitivity of lung cancer cells to cisplatin by targeting miR-556-3p/AK4 axis." (PMID 31931771, 2020). "For example, AK4 is a prognostic marker that facilitates metastasis in lung cancer via silencing ATF3, a transcription factor." (PMID 32549791, 2020). "In same study was demonstrated that downregulation of AK4 restrained lung cancer progression and sensitized lung cancer cells to cisplatin." (PMID 32509571, 2020). "Briefly, AK4 is a downstream target of miR-556-3p and its depletion inhibits lung cancer progression and sensitizes lung cancer cells to cisplatin." (PMID 31931771, 2020). "In the comparison of normal and tumor part in lung cancer samples, AK4 usually overexpressed in tumor part (P < 0.001)." (PMID 31444368, 2019). "Overexpression of AK4 promotes lung cancer metastasis by enhancing HIF-1α stability and EMT under hypoxia." (PMID 30696468, 2019).
lung carcinoma (continued). "Previously, we identified AK4 as a lung cancer progression marker by assessing the correlation between AK4 levels and clinicopathological features." (PMID 30696468, 2019). "Here, we aimed to investigate the impact of AK4 expression on metabolic genes by analyzing lung cancer microarray datasets and decipher the functional consequences on lung cancer metastasis." (PMID 30696468, 2019). "To identify the AK4 metabolic gene signature, we analyzed a lung cancer dataset (GSE31210) that contained microarray data from 246 stage I/II lung adenocarcinoma patients." (PMID 30696468, 2019). "The expression of AK4 and its upstream regulators in lung cancer patients was examined via immunohistochemistry." (PMID 30696468, 2019). "Of note, a previous study found that AK4 promotes the metastasis of lung cancers by downregulating the transcription factor ATF3." (PMID 29866054, 2018). "Additionally, AK4 overexpression promotes lung cancer metastasis by enhancing hypoxia-inducible factor 1α (HIF-1α) stability and epithelial-to-mesenchymal transition (EMT) under hypoxia." (PMID 40593461, 2025). "Moreover, similar to HIF-1, AK4 has been shown to promote chemotherapeutic resistance in tumors and is regarded as an unfavorable prognostic marker for tumor metastasis and lung cancer patient outcomes." (PMID 34940617, 2021). "In lung cancer, adenylate kinase 4 (AK4) promotes metabolic reprogramming and metastasis." (PMID 34638712, 2021). "Moreover, downregulation of AK4 restrained lung cancer progression whereas sensitizes lung cancer cells to cisplatin." (PMID 31931771, 2020). "In summary, AK4 stimulates metastasis of lung cancer by downregulation of ATF3 expression." (PMID 32922364, 2020). "The AK4 has been identified as a biomarker of metastasis in lung cancer." (PMID 32509571, 2020). "The results of this study elucidate that knockdown of circ-ABCB10 sensitized lung cancer cells to cisplatin via miR-556-3p/AK4 axis, which indicated that targeting circ-ABCB10 might be a new thought to improving the efficacy of cisplatin in lung cancer." (PMID 31931771, 2020). "Furthermore, AK4 is a marker of poor clinical outcomes that stimulates the metastasis of lung cancer by downregulation of ATF3 expression." (PMID 32922364, 2020). "AK4 promotes lung cancer malignant progression and recurrence at an ATF3-dependent manner." (PMID 32549791, 2020). "Herein, we validated that AK4 was highly expressed in lung cancer cells." (PMID 31931771, 2020). "Overexpression of AK4 was reported to promote lung cancer metastasis." (PMID 32549791, 2020). "Taken together, our results suggest that AK4 may serve as a critical factor dictating the prognostic power of HIF-1α in lung cancer patients." (PMID 30696468, 2019). "We previously reported that adenylate kinase 4 (AK4) can be used as a lung cancer progression marker that enhances the invasion ability of lung cancer cells and may represent a biomarker of metastasis." (PMID 31444368, 2019). "Interestingly, the GSEA results showed that gene sets categorized as hypoxia response, HIF1A target, glucose metabolism, and lung cancer prognostic genes were significantly enriched in the AK4 metabolic gene signature." (PMID 30696468, 2019). "However, the impact of AK4 expression and/or hypoxia on global glycosylation profile in lung cancer remains to be further elucidated." (PMID 30696468, 2019). "Adenylate kinase 4 (AK4) has been identified as a biomarker of metastasis in lung cancer." (PMID 30696468, 2019). "AK4 overexpression has correlated to poor prognosis and metastasis in lung cancer thus the inhibition of AK4 might provide a potential therapeutic target." (PMID 31444368, 2019). "Since we found that AK4 has a similar function both in non-malignant cells (PASMCs) and lung cancer cells, we can speculate that this might be one possible mechanism underlying the AK4-mediated HIF-1α increase observed in human PASMCs." (PMID 34638712, 2021).
lung carcinoma (continued). "Finally, by correlating the status of AK4 mRNA expression with drug sensitivity data in lung adenocarcinoma cell lines, we proposed lung cancer cells that have high levels of AK4 might be sensitive to EGFR target therapy." (PMID 31444368, 2019). "Adenylate kinase 4 (AK4), has been validated to exert oncogenic function on lung cancer cell growth and metastasis." (PMID 31931771, 2020). "Here, we identified a novel signaling axis whereby enhanced expression of AK4 exaggerates HIF-1α protein expression, leading to EMT induction in lung cancer." (PMID 30696468, 2019). "Therefore we hypothesized that lung cancer cells with AK4-high/AK1-low represent a status of restricted energy demand as pathway and upstream regulator analyses revealed glycolysis and HIF-1α were the predominant metabolic pathway/transcription factor of the gene signatures." (PMID 31444368, 2019). "Withaferin-A suppresses the AK4-HIF-1α signaling axis and serves as a potent anti-metastatic agent against lung cancer, suggesting that it may be a novel therapeutic agent." (PMID 36982634, 2023). "Moreover, it was noticed that AK4 exaggerates HIF-1α protein expression under hypoxia, leading to endothelial to mesenchymal transition in lung cancer." (PMID 34440794, 2021). "More importantly, rescue assays clarified that upregulation of AK4 could reverse the cisplatin-sensitizing and tumor-suppressing effect of circ-ABCB10 knockdown on lung cancer cells." (PMID 31931771, 2020). "Pharmacogenomics analysis of the AK4 gene signature revealed that withaferin-A could suppress the AK4-HIF-1α signaling axis and serve as a potent anti-metastatic agent in lung cancer." (PMID 30696468, 2019). "Additionally, the use of AK4 gene signatures with sPLS-DA identified the nucleotide salvage gene TK1—another negative prognostic marker of lung cancer —to co-express with AK4, and promote LUAD tumor progression as previously reported." (PMID 34940617, 2021). "Moreover, it was found that aferin-A could suppress AK4-HIF-1a signaling and may serve as a novel anti-metastatic agent in lung cancer." (PMID 32509571, 2020). "Taken together, our data suggest that the AK4-HIF-1α signaling axis is a potential therapeutic target of lung cancer metastasis and WFA might be a potential compound for further development to treat metastatic lung cancer." (PMID 30696468, 2019). "Overexpression of AK4 shifts metabolism toward aerobic glycolysis and increases the levels of intracellular reactive oxygen species (ROS), which subsequently stabilizes HIF-1α protein and promotes epithelial-to-mesenchymal transition (EMT) in lung cancer cells in a HIF-1α-dependent manner." (PMID 30696468, 2019). "However, it requires further study to determine whether modulation of AK4 and/or AK1 may overcome T790M-mediated resistance, and through what mechanisms adenylate kinases isoform network may modulate EGFR signaling turn over in lung cancer." (PMID 31444368, 2019).
breast carcinoma (11 papers, 2012 to 2026). "Our current study demonstrates that breast cancer cells have low AK-mediated metabolic flux associated with diminished Ak1 and AK4 expression." (PMID 35712500, 2022). "Other methylation-related mechanisms involved in breast cancer include m6A-mediated epitranscriptomic regulation of the 5′UTR sequence of adenylate kinase 4 (AK4) mRNA by METTL3 through ROS increase and p38 activation conferring resistance to tamoxifen." (PMID 39941901, 2025). "In breast cancer, tamoxifen-resistant cancer cells highly express adenylate kinase 4 (AK4) and METTL3." (PMID 35022030, 2022). "In Tamoxifen-resistant breast cancer cells, the methylation level of m6A-specific motifs in AK4 increased significantly." (PMID 34484567, 2021). "Methyltransferase METTL3 can enhance AK4 expression, increase the level of ROS in breast cancer cells and activate p38 Kinase, and promote the resistance of breast cancer to Tamoxifen, and the role of demethylation ALKBH5 is opposite to that of METTL3." (PMID 34484567, 2021). "In summary, AK4 and P54 proteins may be used as molecular markers for diagnosis and treatment of breast cancer." (PMID 27297086, 2016). "Analysis of the four AK genes (AK1, AK2, AK4, and AK6) mRNA expression in breast cancer cells revealed several alterations in the composition of the AK network." (PMID 35712500, 2022). "For example, the cell survival promoted by overexpressed AK4 under environmental stress and the proliferation of MCF-7 human breast cancer cells in various treatments." (PMID 23020757, 2012).
pancreatic cancer (7 papers, 2020 to 2026). "The AK4 gene played a central role in nucleotide metabolism, and its overexpression in clinical pancreatic cancer samples was frequently linked to adverse patient outcomes." (PMID 42087892, 2026). "Cell-based experiments revealed that AK4 knockdown suppressed pancreatic cancer cell proliferation and migration." (PMID 42087892, 2026). "The impact of AK4, a key gene of nucleotide metabolism, on the proliferation and migration of pancreatic cancer cells was investigated using various molecular biological techniques." (PMID 42087892, 2026). "Expression determination, stage expression detection, and survival analysis revealed that AK4 was significantly upregulated in pancreatic carcinoma tissues and its high expression predicted favourable prognosis in pancreatic carcinoma." (PMID 36476264, 2023). "In addition, TRIM29 controls the transcripts of adenylate kinase 4 (AK4) via posttranscriptional regulation to alter the bioenergetics in pancreatic cancer." (PMID 34988104, 2021). "Moreover, we also demonstrated that AK4P1 might also exert its oncogenic effects through positively regulating AK4 in pancreatic carcinoma." (PMID 36476264, 2023). "However, these works are yet to report the role of AK4 in pancreatic cancer." (PMID 34637398, 2021). "Therefore, MA exerts anti-pancreatic tumor activity by targeting AK4." (PMID 34637398, 2021). "Another study also reported elevated miR-2355-3p enhanced AK4 expression, and miR-2355-3p/DDX3X/AK4 axis was involved in proliferation and invasion of pancreatic cancer cells." (PMID 35611768, 2022). "Mechanistically, MA exerts an anti-pancreatic cancer effect by suppressing the expression of key genes, including UACA and AK4." (PMID 34637398, 2021). "Wound healing experiments further confirmed that overexpression of UACA or AK4 does not influence the migration ability of pancreatic cancer cells." (PMID 34637398, 2021). "The present study revealed that overexpression of AK4 does not affect the proliferation and migration ability of pancreatic cancer cells but could abolish the pancreatic antitumor activity of MA." (PMID 34637398, 2021). "However, the functional roles and the clinicopathological significance of AK4 and DGKH in pancreatic cancer have never been investigated." (PMID 33194391, 2020).
osteosarcoma (6 papers, 2018 to 2025). A usually aggressive malignant bone-forming mesenchymal neoplasm, predominantly affecting adolescents and young adults. "AK4 also acts as a carcinogen in ovarian carcinoma and is associated with multidrug resistance in osteosarcoma cell lines." (PMID 35664305, 2022). "Many studies indicate that chemoresistant Osteosarcoma cells overexpress AK4, an important enzyme that plays an important role in cellular energy homeostasis and stress response." (PMID 40429954, 2025). "Researchers have conclusively identified that miR-199a-3p acts as an important regulator of high levels of chemoresistance in Osteosarcoma by directly targeting adenylate kinase 4 (AK4)." (PMID 40429954, 2025). "In addition, a classical tumor suppressor known as miR-34a has been found to inhibits osteosarcoma through multiple targets; MiR-199a-3p was found to be able to inhibit osteosarcoma as well by targeting Adenylate Kinase 4 (AK4), and so on." (PMID 36038837, 2022).